PPARG (peroxisome proliferator activated receptor gamma)
Diseases named in the same sentence as PPARG in open-access papers (continued):
Sharing a sentence is not in itself a finding about the gene and the disease.
Obesity (continued). "Also, it was studied whether the Pro12Ala polymorphism of peroxisome proliferator-activated receptor γ (PPARγ) is related to insulin resistance, obesity, and weight loss and the potential interactions between fat intake and PPARγ polymorphism was explored." (PMID 28678155, 2017). "However, PPARγ plays a role in adipocyte differentiation and adipogenesis, and the increased expression of this receptor has been implicated in obesity." (PMID 27588004, 2016). "Apart from epigenetics, we should not lose sight of the fact that metabolic syndrome, insulin resistance, obesity, and inflammation, importantly interrelated conditions in which PPARG has modifying and regulatory actions, increase cancer risk, which adds weight to PPARG and cancer research." (PMID 27579030, 2016). "However, in light of the particular role of PPARγ in adipose tissue development and maintenance, it has been suggested that the disruption of regulatory pathways controlled by PPARγ may be specifically implicated in the onset of diabetes and obesity." (PMID 26029163, 2015). "We identified PPARγ as a potential target of Twist 1 and found variation in the secretion of multiple adipokines, which might indicate a prospective mechanism linking Twist 1 expression with obesity or associated diseases." (PMID 25128964, 2014). "PPARγ appears therefore to be a key regulator of adiposity and energy balance and may be one of the most important genetic factors in predisposing individuals to obesity." (PMID 23545576, 2013). "Since activation of PPARγ is associated with increased adiponectin expression, inhibition of PPARγ by nuclear factor kappa B (NFκB) during obesity could be a potential link between obesity and reduced adiponectin expression." (PMID 23189205, 2012). "The pathophysiology of obesity and type 2 diabetes mellitus is associated with abnormalities in endocrine signaling in adipose tissue and one of the key signaling affectors operative in these disorders is the nuclear hormone transcription factor peroxisome proliferator-activated receptor-γ (PPARγ)." (PMID 19300518, 2009). "Collectively, these findings suggest that EA prevents HFD-induced obesity by alleviating intestinal oxidative stress and mitochondrial dysfunction through the modulation of the PPARG/STAT3/p-AKT1 signaling axis." (PMID 41829165, 2026). "It is strongly associated with HS, among other dermatoses, as evidenced by the dysregulated expression of proteins related to metabolism/obesity (PPARγ, IGF-1R, and irisin)." (PMID 40869025, 2025). "Taken together, the findings show that freeze-dried kimchi cabbage and onion modulated obesity by regulating adipogenesis and lipogenesis via the C/EBPα and PPARγ pathways." (PMID 41189663, 2025). "This promotes lipolysis and fatty acid oxidation while suppressing PPARγ, collectively contributing to a pronounced anti-obesity effect." (PMID 41488302, 2025). "Examining the primary markers associated with obesity and adiposity, including SREBP-1, AMPK, PPARγ, and perilipin, has provided promising evidence for these findings." (PMID 40509530, 2025). "Previous studies have reported a positive correlation between MEG3 and lipogenic genes, such as FASN and PPARG, in the subcutaneous adipose tissue of females with obesity." (PMID 40806129, 2025). "This extended presence subsequently potentiated its agonistic effect on PPARγ, thereby exacerbating hepatic lipid accumulation and ultimately triggering an obesity‐specific DILI." (PMID 39611414, 2025). "The Wnt/β‐catenin signaling pathway prevents obesity by inhibiting C/EBPα and PPARγ signaling pathways." (PMID 41211169, 2025). "Several relevant transcription factors (TFs) bind to the promoter region of ZPR1, including PPARG (functioning in insulin sensitivity and obesity) and HNF4A (triggering genes involved in glucose, fatty acid, and cholesterol metabolism)." (PMID 40665476, 2025).
Obesity (continued). "For instance, sesamin and sesamolin, major sesame lignans, controlled obesity by downregulating C/EBPα and PPARγ expression." (PMID 41189663, 2025). "In line with this, anti-inflammatory and pro-healing actions of pharmacological PPARγ agonists such as rosiglitazone in mouse woundγ models of diabetes and obesity have been described." (PMID 40906806, 2025). "Gene expressions of Pparγ and Nrf2 were increased by obesity in both experimental groups (p < 0.001)." (PMID 39576482, 2025). "In obesity‐driven IR, dietary strategies that activate PPARγ or reduce BCAA intake can attenuate mTOR hyperactivation, thereby improving metabolic outcomes." (PMID 40673471, 2025). "Cnot4 promotes adipocyte differentiation partly through PPARγ, and it likely contributes to hyperplasia in enlargement of adipose tissues during obesity." (PMID 40424271, 2025). "In obesity, vanillic acid acts by inhibiting adipogenesis markers PPARγ and C/EBPα, activating the AMPK signaling pathway, reducing lipid accumulation and inflammation, promoting thermogenesis, enhancing glucose tolerance, and improving insulin resistance." (PMID 39850111, 2025). "C/EBPα and PPARγ play critical roles in obesity via modulation of the expression of the adipogenic biomarkers." (PMID 41189663, 2025). "This study demonstrates that the RRTFB improves alleviates obesity and its associated metabolic complications through epigenetic regulation of the DNMT3a/SIRT1/PPARγ axis." (PMID 40909259, 2025). "The expression of PPARG is significantly higher in patients with obesity and positively correlated with BMI, waist circumference, and weight-hip ratio." (PMID 40985048, 2025). "Obesity drives systemic inflammation and metabolic dysfunction through epigenetic modifications, including altered methylation of genes like PPARγ and GLUT4 and changes in histone acetylation that regulate metabolic pathways and inflammatory responses." (PMID 40458403, 2025). "This extended presence subsequently potentiates its agonistic effect on PPARγ, thereby exacerbating hepatic lipid accumulation and ultimately triggering an obesity‐specific drug‐induced liver injury (DILI)." (PMID 39611414, 2025). "Future studies should validate ginsenoside Rg5 in vivo, particularly in models of diet-induced obesity, to assess its efficacy in ameliorating metabolic dysregulation while circumventing the side effects characteristic of classical PPARγ agonists." (PMID 40405893, 2025). "Peroxisome proliferator-activated receptor gamma (PPARγ) is a key target for metabolic disorders that contribute to obesity and type 2 diabetes mellitus (T2DM)." (PMID 40405893, 2025). "Collectively, these findings suggest that PRLE inhibits adipocyte differentiation both in vitro and in vivo in high-fat diet-induced obesity through the suppression of PPARγ." (PMID 41155630, 2025). "Among the PTMs, acetylation at K268/K293 of PPARγ is heightened in adipose tissue under obesity and aging and shows a diurnal rhythm orchestrated with metabolic oscillation." (PMID 41473291, 2025). "By combining exome-wide association analysis of traits related to obesity and fat distribution with CRISPR gene perturbation in human fat cells, this study highlights genes linked with fat accumulation, including SLTM, PPARG, and COL5A3." (PMID 40912257, 2025). "In conditions like obesity or when adipocytes undergo hypertrophy, the normal upregulation of adiponectin by PPARγ is hindered, leading to reduced adiponectin expression." (PMID 40596724, 2025). "Taken together, these data support that increasing 15-keto-PGE2 via inhibition of its degrading enzymes as a feasible approach to activate PPARγ and treat diabetes and obesity." (PMID 40119175, 2025). "According to a recent study, TMEM18 is an upstream regulator of PPARG signaling driving healthy adipogenesis, which is dysregulated with adipose tissue dysfunction and obesity." (PMID 41082226, 2025).
Obesity (continued). "Lupeol has been found to reduce the expression of C/EBPα, PPARγ, and inflammatory cytokines in 3T3-L1 cells as well as animal models of obesity." (PMID 39858523, 2025). "In molecular biology, 1,25(OH)2D regulates the development and differentiation of adipocytes and alleviates obesity by inhibiting the expression of peroxisome proliferator-activated receptor γ (PPARγ)." (PMID 40362671, 2025). "In the setting of decreased PPARγ expression in obesity, the typical pattern observed includes limiting further AT expansion and dysregulating adipokine production and release patterns, including low levels of adiponectin and high levels of leptin." (PMID 40871639, 2025). "Previous study also found the modulation role of conjugated fatty acid on peroxisome proliferator-activated receptor gamma in obesity and inflammatory bowel disease." (PMID 40367711, 2025). "For example, pro‐inflammatory pathways (NF‐κB, JNK) and cytokine signaling (e.g., CRP, IL‐1β) drive IR and β‐cell stress, while PPARγ and leptin signaling mediate obesity‐driven IR." (PMID 40673471, 2025). "PPARγ plays anti-inflammatory roles in obesity, metabolic syndrome, insulin resistance/insufficiency, type 2 diabetes mellitus, and inflammation." (PMID 40069892, 2025). "Curcumin’s anti-obesity effects arise from its ability to inhibit adipogenesis and lipid buildup, mainly by downregulating adipogenic transcription factors, such as PPARγ and C/EBPα." (PMID 40868165, 2025). "Moderate polyphenol intake can reduce adipogenesis, promote fatty acid oxidation, and increase energy expenditure by activating pathways such as AMPK/SIRT1 and inhibiting PPARγ, thereby exerting anti-obesity effects." (PMID 41008164, 2025). "Collectively, these findings suggest that HPWE inhibits adipocyte differentiation both in vitro and in vivo in high-fat diet-induced obesity through the suppression of PPARγ." (PMID 41155164, 2025). "Obesity-induced extracellular miR-27a inhibits the expression of the transcription factor peroxisome proliferator-activated receptor γ (PPARγ), which inhibits the production of inflammatory cytokines." (PMID 40565979, 2025). "Activation ofPPARα and PPARγ have adverse outcome pathways resultingin vascular disruption, obesity, liver steatosis, cancers, and reproductivedysfunction." (PMID 39839249, 2025). "In this context, we conducted a molecular docking study to explore potential PPARγ antagonists as anti-obesity therapeutic candidates." (PMID 41007669, 2025). "PPI analysis revealed MTNR1B’s strong association with diabetes, obesity, cancer, and circadian rhythm disorders, collectively known as circadian syndrome, and MTNR1B’s close interaction with thermogenic genes (UCP1, PPARG, and PPARGC1A)." (PMID 40697662, 2025). "Meanwhile, PPARγ overactivation promotes adipogenesis and lipid uptake, leading to obesity and sustained systemic insulin resistance and inflammation, further exacerbating metabolic dysfunction." (PMID 40282189, 2025). "In reaction to obesity, adipose tissue macrophages release more miR-155, which targets PPARγ and inhibits insulin signaling in muscle cells, hepatocytes, and adipocytes." (PMID 40565979, 2025). "Pck1 is a regulator of the energy metabolism and gluconeogenesis in the liver, and its imbalance is related to metabolic diseases, such as diabetes, obesity and insulin resistance, while there is also a certain correlation between PPARγ and Pck1." (PMID 40786039, 2025). "Endocrine‐disrupting chemicals alter the glucocorticoid and PPARγ pathways to promote hyperphagia, inflammation, adipocyte hyperplasia and hypertrophy, and obesity." (PMID 39825581, 2025). "HFD-induced obesity overactivates PPARγ, leading to increased lipid accumulation and systemic insulin resistance." (PMID 40282189, 2025).
Obesity (continued). "This approach not only accelerates the identification of safer, tissue-selective PPARγ modulators but also bridges traditional pharmacopeias with modern structure-based drug design, offering a sustainable strategy to combat obesity-related metabolic disorders." (PMID 40405893, 2025). "Evidence suggests that PPARα and PPARβ/δ are potential therapeutic targets to prevent obesity, while PPARγ, a master regulator of adipogenesis, modulates obesity-related phenotypes." (PMID 41438090, 2025). "This supports the use of PPARγ agonists, such as rosiglitazone and pioglitazone, in managing diabetes and obesity in atherosclerosis patients." (PMID 40114970, 2025). "Based on mRNA and protein expression, we concluded that the freeze-dried kimchi cabbage and onion modulated obesity via regulation in the C/EBPα and PPARγ pathways." (PMID 41189663, 2025). "Macrophage-specific knockouts have revealed the importance of PPARγ in macrophage function and protection against the metabolic consequences of obesity by maintaining insulin sensitivity and glucose tolerance." (PMID 39857594, 2024). "The Lgals1 gene plays an important role in adipocyte differentiation and the development of obesity, particularly through its interaction with and influence on the activity of PPARγ." (PMID 39040415, 2024). "Phosphorylation of PPARγ’s serine 273 residue demonstrated no alteration of PPARγ’s adipogenic induction but altered a subset of PPARγ target genes expression that are commonly dysregulated in obesity including adiponectin and adipsin." (PMID 38781157, 2024). "The appropriate transcriptional activity of PPARγ is indispensable for controlling inflammation, tumor and obesity." (PMID 38332049, 2024). "As we saw the level of Obr was increased with diet‐induced obesity, and the transcription factor Pparγ involved in lipid metabolism regulated the expression of Obr, we verified the possible mechanism by which Obr was upregulated in response to HFD." (PMID 38704700, 2024). "We have recently provided evidence that PPARγ undergoes epigenetic regulation, and any rearrangements lead to numerous metabolic disorders such as obesity or insulin resistance." (PMID 39595621, 2024). "These molecules were found to interact with key obesity-related genes, notably PPARG, highlighting their relevance in obesity treatment." (PMID 39744140, 2024). "We propose the anti-obesity effect of OKE based on the results showing that OKE significantly reduced the expression of PPARγ, C/EBPα, and AP2 during differentiation and ultimately inhibited lipid accumulation in adipocytes." (PMID 38732125, 2024). "Molecular docking and molecular dynamics simulations underscore the similarities in binding affinities and interactions among curcumin and its derivatives with pivotal anti-obesity target proteins—PPARγ, COX2, and FAS." (PMID 38473849, 2024). "In the context of obesity, the peroxisome proliferator-activated receptor gamma (PPAR-γ) and microRNA-21 (miR-21) play significant roles." (PMID 39195481, 2024). "FTO is a major genetic link between breast cancer, obesity, and diabetes PPARG regulates adipocyte differentiation, lipid storage, and glucose metabolism, affecting insulin sensitivity and linking it to obesity, metabolic syndrome, and type 2 diabetes." (PMID 39769194, 2024). "Hypothalamic PPARγ mRNA expression was several folds higher in mice with diet-induced obesity than in the lean controls." (PMID 39201373, 2024). "Studies have shown that in mice, inactivation of Usf1 significantly improves diet-induced dyslipidemia, obesity, IR, hepatic steatosis, and atherosclerosis, while NASH is associated with IR and increased expression of PPARγ in the liver." (PMID 39840059, 2024). "The study highlighted the significance of PI3K-Akt and PPAR signaling pathways, particularly focusing on AKT1 and PPARG, which demonstrated extensive protein-protein interactions among obesity-related genes." (PMID 39409084, 2024).
Obesity (continued). "During diet-induced obesity, mice develop insulin resistance and exhibit increased PPARγ Ser-273 phosphorylation in WAT." (PMID 38735390, 2024). "Another study noticed the synergistic impact of other genes such as peroxisome proliferator-activated receptor gamma (PPARγ), FTO, and melanocortin-4 receptor (MC4R)—in the predisposition to overweight and obesity." (PMID 38397196, 2024). "Genes such as FTO (fat mass and obesity-associated gene), LEP (leptin), MC4R (melanocortin 4 receptor), and PPARG (peroxisome proliferator-activated receptor gamma) are well-established contributors to obesity susceptibility." (PMID 39390356, 2024). "Treating obesity and type 2 diabetes with PPARG and RXR antagonists can reduce triglyceride content in white adipose tissue, increasing fatty acid burning and energy expenditure." (PMID 39208245, 2024). "In this respect, D-mannose is obviously different from glucose and initiates a complex of ACSS2 and PPARγ to target Ucp1 transcription, thereby improving obesity and its related disorders, such as glucose utilization, insulin sensitivity and liver steatosis." (PMID 38332049, 2024). "Overall, the results indicate that sitogluside, followed closely by cycloartenol, exhibits strong binding and stabilizing interactions with PPARG, providing a molecular basis for their potential anti-obesity effects." (PMID 39744140, 2024). "Here we have described the evidence-based selection of suitable chemicals for the development and validation of PPARα and PPARγ as molecular-level events, and white adipose tissue adipogenesis as an apical organ/tissue-level adverse effect for obesity." (PMID 39040675, 2024). "Among them, butyric acid affects obesity by modulating the function of the gut barrier-activated peroxisome proliferator γ (PPARγ)." (PMID 39458990, 2024). "Studies found that ZRR and its active compounds are bioactive, inducing cancer cell apoptosis by inhibiting STAT3 and NFκB, repressing inflammation by inhibiting NFκB, and fighting obesity by upregulating PPARγ." (PMID 39338294, 2024). "The gut microbiota plays a significant role in metabolic disorders such as diabetes and obesity, with the peroxisome proliferator-activated receptor gamma (PPAR-γ) being a key regulator in adipogenesis and glucose metabolism." (PMID 39943964, 2024). "As a result, quercetin can either negate the effects of antagonism caused by inflammatory stimuli on PPARγ or directly activate PPARγ to increase its anti-obesity efficacy." (PMID 38674793, 2024). "Several in silico studies have suggested that γ-sitosterol exerts PPARγ agonistic properties, which is effective against obesity and alcoholic liver disease." (PMID 39338294, 2024). "Together, these results suggested that the response of IMAT-resident PPARγ+ macrophages to S-FAs increases with BMI and obesity." (PMID 39857594, 2024). "The present study examined PPARγ+ macrophages in human skeletal muscle tissues, their response to fatty acid (FA) species, and their correlations with age, obesity, adipokine expression, and an abundance of other macrophage phenotypes." (PMID 39857594, 2024). "Currently, there have been no Food and Drug Administration (FDA)-approved drugs targeting AKT1 and PPARG pathways specifically for regulating lipid metabolism in anti-obesity treatment." (PMID 39409084, 2024). "PPARγ, as an essential regulator of adipogenesis, has been a primary target in the development of numerous anti-obesity drugs." (PMID 39195446, 2024). "To study the underlying molecular mechanism of the anti-obesity effect of ABS in adipocytes, we also conducted the immunofluorescence analysis of β-catenin, C/EBPα, and PPARγ in the 3L3-L1 cell line." (PMID 39594522, 2024). "Accordingly, PPARγ and CEBPα are extensively utilized as targets for the development of anti-obesity drugs through the inhibition of adipogenesis, both in vitro and in vivo." (PMID 39210615, 2024).